Y_RNA (Y RNA )
Gene: Miscellaneous RNA gene on chromosome 11 (72,766,004 to 72,766,116, forward strand). Ensembl gene ENSG00000202522.
Homologues: Orthologues: chimpanzee Y_RNA (100% identical), macaque Y_RNA (99% identical). Paralogues in human: RNY1 (92% identical), Y_RNA (88% identical), RNY1P11 (87% identical), Y_RNA (87% identical), Y_RNA (86% identical), Y_RNA (85% identical), RNY1P8 (84% identical), Y_RNA (84% identical), RNY1P5 (83% identical), Y_RNA (83% identical), RNY1P12 (82% identical), Y_RNA (82% identical), and 96 more.